PDCD11 (programmed cell death 11)
Description:
Essential for the generation of mature 18S rRNA, specifically necessary for cleavages at sites A0, 1 and 2 of the 47S precursor. Directly interacts with U3 snoRNA. Involved in the biogenesis of rRNA.
Synonyms: NFBP; KIAA0185; ALG-4; RRP5; ALG4
Tractability: PROTAC: UniProt records ubiquitination sites on it; ubiquitination databases record sites on it; its protein half-life has been measured.
Gene: Protein-coding gene on chromosome 10 (103,396,626 to 103,446,297, forward strand). Ensembl gene ENSG00000148843.
Subcellular location: Nucleus, nucleolus
Subcellular location (Human Protein Atlas): Nucleoli rim; Vesicles
Pathways (Reactome):
Metabolism of RNA: Major pathway of rRNA processing in the nucleolus and cytosol; rRNA modification in the nucleus and cytosol
Gene Ontology:
Molecular function: NF-kappaB binding; protein binding; RNA binding; nucleic acid binding
Biological process: RNA processing; rRNA processing
Cellular component: nucleolus; nucleus; nucleoplasm; small-subunit processome; cytosol
Genetic constraint (gnomAD): Loss-of-function variants: 84 observed, 175.74 expected, observed/expected ratio (o/e) 0.48, 90% interval 0.4 to 0.57. The upper end of that interval is the gene's LOEUF score, 0.57, which puts it in group 2 of 6, group 1 being the genes least tolerant of losing a copy. Missense variants: 2,006 observed, 2,280 expected, observed/expected ratio (o/e) 0.88, 90% interval 0.85 to 0.91. Synonymous variants: 858 observed, 906.75 expected, observed/expected ratio (o/e) 0.95, 90% interval 0.89 to 1.
Homologues: Orthologues: chimpanzee PDCD11 (99% identical), macaque PDCD11 (98% identical), dog PDCD11 (88% identical), rabbit PDCD11 (88% identical), pig PDCD11 (86% identical), rat Pdcd11 (81% identical), guinea pig PDCD11 (81% identical), mouse Pdcd11 (81% identical), tropical clawed frog pdcd11 (49% identical), zebrafish pdcd11 (42% identical), Caenorhabditis elegans let-716 (23% identical), Drosophila melanogaster Rrp5 (20% identical).
Diseases named in the same sentence as PDCD11 in open-access papers:
PDCD11 is named in the same sentence as 24 diseases in open-access papers, as found by Europe PMC text mining. Sharing a sentence is not in itself a finding about the gene and the disease. The quoted sentences say what the papers report.
colon cancer (2 papers, 2023 to 2025). "PDCD11 displays a higher level in tumor than in normal samples for several cancer types including CRC (COAD: colon cancer + READ: rectal cancer)." (PMID 38062028, 2023).
Stroke (2 papers, 2018 to 2022). Sudden impairment of blood flow to a part of the brain due to occlusion or rupture of an artery to the brain. "Of these, programmed cell death 11 (PDCD11) was determined to be associated with stroke (p < 0.0001), as evidenced from the second screening using AlphaLISA." (PMID 29507658, 2018). "A strong association was observed between PDCD11-Ab levels and hypertension (p < 0.0001), diabetes (p = 0.0003), and stroke (p < 0.0001)." (PMID 29507658, 2018). "DDX18 was identified to be associated with stroke, and serum PDCD11-AB levels may serve as a potential biomarker for TRANSIENT ischemic attack." (PMID 35571562, 2022). "The major finding of this study is that PDCD11-Ab levels were elevated in patients with symptomatic stroke, which turned out to be an independent predictor of TIA." (PMID 29507658, 2018). "To validate the elevated levels of PDCD11-Abs in stroke patients, we further examined PDCD11-Ab levels in the independent validation cohort (n = 906)." (PMID 29507658, 2018). "Immunological research would further verify the mechanisms of PDCD11-Ab elevation in the sera of patients with TIA and stroke." (PMID 29507658, 2018). "On the other hand, serum PDCD11-Ab levels were elevated only in patients with TIA and stroke but not in those with AMI and DM." (PMID 29507658, 2018). "If HDs without any symptoms have a high level of PDCD11-Ab on this test, they could have high risks for TIA or stroke." (PMID 29507658, 2018).
acute myocardial infarction (1 paper, 2018). Necrosis of the myocardium, as a result of interruption of the blood supply to the area. "We further examined correlations between PDCD11-Ab levels and acute myocardial infarction (AMI) and diabetes mellitus (DM) in the other validation cohort using sera of each 128 age-matched patients and HDs." (PMID 29507658, 2018).
asthma (1 paper, 2022). "We found PDCD11 was negatively associated with asthma-related TFs, including WT1, ZEB1, and RERE; ALDH18A1 was negatively associated with WT1 and RERE; SEC61A1 was negatively related with WT1 and ZEB1." (PMID 35169275, 2022). "Hence, PDCD11, ALDH18A1, and SEC61A1 may play a role in the development of asthma through transcriptional regulation-related mechanisms." (PMID 35169275, 2022).
colorectal cancer (1 paper, 2023). A primary or metastatic malignant neoplasm that affects the colon or rectum.
colorectal tumors (1 paper, 2023). "By interrogating The Cancer Genome Atlas (TCGA) and the Genotype-Tissue Expression (GTEx) databases, we found another nucleolar protein, programmed cell death 11 (PDCD11), overexpressed in colorectal tumors and highly related to CRC progression." (PMID 38062028, 2023).
diabetes (1 paper, 2018). "In our opinion, the diagnostic value will improve by a combination of the measurement of the PDCD11-Ab and clinical risk factors, including age, hypertension, and diabetes, which were independent predictive factors for TIA in the multivariate logistic regression analysis." (PMID 29507658, 2018). "Predictive value of PDCD11-Ab for TIA was not inferior to other known risk factors of TIA including age (OR: 4.97, 95% CI: 2.67-9.48, p < 0.0001); hypertension (OR: 3.21, 95% CI: 1.76-5.86, p = 0.0001); and diabetes (OR: 4.31, 95% CI: 1.74-11.2, p = 0.0015)." (PMID 29507658, 2018).
ischemia (1 paper, 2018). A hypoperfusion of the BLOOD through an organ or tissue caused by a PATHOLOGIC CONSTRICTION or obstruction of its BLOOD VESSELS, or an absence of BLOOD CIRCULATION. "This intriguing finding led us to hypothesize that the immune response against PDCD11 is not due to the leakage of PDCD11 from atherosclerotic plaques but due to the leakage from brain tissues exposed to ischemia." (PMID 29507658, 2018).
ischemic stroke (1 paper, 2018). A stroke disorder caused by obstruction of blood flow to the brain, due to thrombotic (local blood clot formation) or embolic (due to a blood clot or other material traveling from another site) event. "Because PDCD11-Ab levels were elevated specifically in sera from patients with ischemic stroke, we further examined PDCD11 protein expression in surgically-resected ischemic brain tissue using immunohistochemistry." (PMID 29507658, 2018). "As the overexpression of cancer -related antigens stimulate the immunity and produce their autoantibodies, overexpression of PDCD11 in ischemic brain tissue might also stimulate autoimmune response and produce the PDCD11 autoantibody in patients with ischemic stroke." (PMID 29507658, 2018).
cancer (3 papers, 2018 to 2025). A tumor composed of atypical neoplastic, often pleomorphic cells that invade other tissues. "PDCD11 silencing markedly reduced the migration rates of MDA‐MB‐231 and HT‐29 cells (p < 0.05), indicating that PDCD11 promotes metastasis by regulating cancer cell migration." (PMID 40051297, 2025). "By facilitating the G1/S transition and migration, PDCD11 functions as an oncoprotein to accelerate cancer cell growth and metastasis." (PMID 40051297, 2025). "Downregulation of PDCD11 greatly reduced cancer cell growth in vitro and in vivo, additionally sensitized cells to DNA damage signals, highlighting that PDCD11 is a crucial driving factor of CRC and a potential target for cancer treatment." (PMID 38062028, 2023). "We concluded that PDCD11 is an “Extra-nucleolar” oncoprotein to promote cancer cell growth and survival by regulation of G2/M checkpoint and DNA damage signaling, highlighting a potential novel target for treating CRC." (PMID 38062028, 2023). "Collectively, high-level PDCD11 indicates a poor prognosis in CRC and acts as an oncoprotein to accelerate cancer cell growth through facilitating cell-cycle transition from G2 to M phase." (PMID 38062028, 2023). "On the other hand, SKP2 helps C‐MYC retain its TFA in PDCD11‐overexpressed cancer cells, which is not weakened by hindered interaction with SKP2." (PMID 40051297, 2025).
tumor (2 papers, 2023 to 2025). "Considering that the Kaplan‐Meier survival curves revealed the correlation between PDCD11 levels and tumor metastasis, we performed a transwell assay to verify this." (PMID 40051297, 2025). "Our findings also highlight the contribution of the C‐MYC‐SKP2 axis to PDCD11‐driven tumor progression." (PMID 40051297, 2025). "More importantly, these findings suggest that “extra-nucleolar” RSL1D1 and PDCD11 should be potential tumor markers in CRC theranostics." (PMID 38062028, 2023). "Additionally, we found that PDCD11 silencing significantly decreased Ki67 levels (p < 0.001), a canonical marker indicating tumor cell proliferation, in both MDA‐MB‐231 and HT‐29 tumors, further confirming the antitumor efficacy of shPDCD11." (PMID 40051297, 2025). "Consistent with the results of TCGA, Kaplan‐Meier analyses, and oncogenic phenotype assays, Reactome enrichment and Disease Ontology (DO) enrichment analyses revealed that PDCD11 promotes tumorigenesis and tumor progression by regulating G1/S transition during cell cycle progression." (PMID 40051297, 2025). "PDCD11 silencing decreased the levels of the C‐MYC oncoprotein and its target genes, including SKP2, leading to suppressed tumor progression." (PMID 40051297, 2025). "Through interaction with C‐MYC in the nucleoplasm, PDCD11 hinders C‐MYC‐induced SKP2 from binding to the C‐MYC MB2 domain for ubiquitination, thereby stabilizing C‐MYC to drive tumor progression." (PMID 40051297, 2025). "PDCD11 silencing restores SKP2‐mediated C‐MYC degradation, thereby remarkably suppressing tumor growth and metastasis in nude mice." (PMID 40051297, 2025). "By antagonizing SKP2‐mediated C‐MYC ubiquitination, PDCD11 disrupts the balance between C‐MYC and SKP2, resulting in uncontrolled C‐MYC signaling and tumor progression." (PMID 40051297, 2025). "Our findings provide a PDCD11‐targeted therapeutic rationale for specially degrading the C‐MYC oncoprotein by efficiently harnessing the SCFSKP2‐possessed E3 ubiquitination activity, which results in a reduced SKP2 expression to avoid triggering SKP2‐promoted tumor progression." (PMID 40051297, 2025). "Thus, PDCD11 upregulates C‐MYC protein but not C‐MYC mRNA to activate downstream effector molecules including but not limited to E2F1, CCNE2, and SKP2, thereby exerting its tumor‐promoting functions." (PMID 40051297, 2025).
cardiovascular disease (1 paper, 2018). "PDCD11-Ab levels were higher in females than in males (p = 0.0073); moreover, the association was higher in patients with cardiovascular disease (CVD) than those without the disease (p = 0.0011)." (PMID 29507658, 2018).
PDCD11 also shares sentences with these, for which no sentence is quoted: breast carcinoma (1 paper); breast tumors (1); hepatocellular carcinoma (1); hyperlipidemia (1); Hypertension (1); infection (1); Infertility (1); Obesity (1); rectal cancer (1); sterility (1); transient ischemic attack (1); triple-negative breast carcinoma (1).